VIM (vimentin)
Diseases named in the same sentence as VIM in open-access papers (continued):
Sharing a sentence is not in itself a finding about the gene and the disease.
sarcoma (continued). "In two poorly differentiated sarcomas, tumour cells expressed Iba-1 and vimentin (clone V9) and were negative for desmin and α-SMA, so they were reclassified as histiocytic sarcomas." (PMID 35454212, 2022). "The expression of vimentin was positive in sarcoma components, while negative in other adjacent tissue components, indicating a heterogenous status of CSB." (PMID 35865143, 2022). "In sarcomas, cells are positive for Vimentin and S-100, and they are negative for CK, CK7, EMA, and HMB45." (PMID 35029195, 2022). "In the poorly differentiated sarcoma, tumour cells expressed vimentin (clone 3B4) but were negative for Iba-1, α-SMA and desmin." (PMID 35454212, 2022). "For sarcomas, vimentin is used to identify CTCs, as sarcomas are not epithelial in origin and thus do not express cytokeratins." (PMID 35327389, 2022). "Immunohistochemistry tests for desmin, vimentin, α‐SMA, CK, leukocyte common antigen (LCA), CD34, human melanoma black 45 (HMB45), epithelial membrane antigen (EMA), and S100 are performed in sarcomas to differentiate other tumor types and make a final diagnosis." (PMID 36093467, 2022). "In poorly differentiated sarcomas, tumour cells expressed vimentin (clone V9) and α-SMA and were negative for Iba-1 and desmin." (PMID 35454212, 2022). "Although these tumors are morphologically sarcoma-like, immunohistochemical examination shows them to be negative for muscular markers and positive for epithelial (e.g., cytokeratin AE1/AE3) and mesenchymal cell markers (e.g., vimentin)." (PMID 33903966, 2021). "Consistently, IHC negative for CK20, CDx2, TTF-1, CD10 and Vimentin excluded urothelial, gastrointestinal, lung, thyroid, kidney cancer and sarcoma metastasis." (PMID 33912469, 2021). "Additionally, we found that CNN3 mRNA expression had a significant positive correlation with the mRNA expression of two mesenchymal markers, Snail and vimentin (VIM), and two tumor proliferation markers, MKI67 and PCNA, in sarcoma." (PMID 32667904, 2020). "Immunocytochemistry for vimentin was performed on the cell lines that did not have xenograft sarcoma confirmation (i.e. D9, M3, N3-1, O7, Q8-1, Sh4, and Y5) Vimentin expression was detected in all 7 cell lines." (PMID 30498397, 2018). "Immunohistochemically, this sarcoma expresses S-100, CD1a, and vimentin, but is consistently negative for follicular dendritic cell markers." (PMID 26762155, 2016). "Generally, malignant epithelial tumours such as carcinomas have keratin intermediate filaments, whereas malignant non-epithelial tumours such as sarcomas possess vimentin filaments." (PMID 26477839, 2015). "Biopsy of renal mass revealed poorly differentiated sarcoma and IHC was positive for vimentin, CD99, and BCL2 and negative for AE1, epithelial membrane antigen, and leukocyte common antigen." (PMID 25610686, 2014). "Although the tumour showed biphasic appearances on haematoxylin and eosin, it exhibited poor protein expression with most sarcoma markers being negative except for focal vimentin positivity." (PMID 23476861, 2013). "Notably, in sarcoma cells, TIM-3 was co-expressed with certain biomarkers of epithelial-mesenchymal transition (EMT), including vimentin, Slug, Snail and Smad." (PMID 24137353, 2013). "It was this focal epithelioid differentiation that favoured our final diagnosis of SpCC even though the spindle-cell components were negative for all the epithelial markers and most of sarcoma markers except for focal immunopositivity of vimentin." (PMID 23476861, 2013). "Our patient's immunohistochemistry test results were negative for cytokeratin, vimentin, and CD-31 and CD-34, allowing us to exclude a likely diagnosis of adenocarcinoma, sarcoma, or vascular tumor, respectively." (PMID 21801379, 2011). "The present case is not carcinocarcoma or sarcoma, because the sarcomatoid giant tumor cells were positive for cytokeratins and vimentin and negative for other mesenchymal antigens." (PMID 20062688, 2009).
sarcoma (continued). "The sarcoma was immunohistochemically positive for vimentin but negative for cytokeratins and other mesenchymal markers." (PMID 27933124, 2009). "Furthermore, the IHC for CK20, CDx2, TTF1, CD10 and Vimentin showed a negative result, thus excluding metastases from gastrointestinal, lung, thyroid, renal cancer as well as sarcoma, respectively." (PMID 33912469, 2021). "However, in sarcomas, the role of vimentin as a tumor marker has not been explored deeply due to its ubiquitous expression." (PMID 28910304, 2017). "There was no staining in the sarcoma cells for pan-CK while vimentin were positive." (PMID 22943261, 2012). "Therefore, the expression of vimentin and snail might not be sufficient to explain the invasiveness of sarcoma cells and the concept of EMT in osteosarcoma poses a paradox." (PMID 31215499, 2019). "Despite their sarcoma‐like morphology, these cells often co‐express epithelial (cytokeratin AE1/AE3) and mesenchymal (vimentin) markers and are typically negative for muscular lineage proteins." (PMID 40115691, 2025). "However, Intimal sarcoma is poorly differentiated malignant tumor, which is difficult to distinguish from other malignancies only in terms of tissue and cell morphology, and the immunohistochemical phenotype lacks specificity, vimentin 、SMA are positive, others are mostly negative." (PMID 40017520, 2025). "Remarkably, even broadly mesenchymal markers vimentin and CD68 were negative, a finding typically seen in undifferentiated pleomorphic sarcomas." (PMID 35501497, 2023). "Tumor cells are consistently positive with S100 and Vimentin, which are mostly negative in FDC/FRC sarcoma." (PMID 34514557, 2021). "In our case, histopathological examination revealed the same morphological appearance, with low Ki-67 expression (<1 %), rare mitoses, and myofibroblastic differentiation (vimentin/SMA/desmin positive, S100 negative), ruling out high-grade sarcoma and neurogenic tumors." (PMID 40674963, 2025). "In addition, positive staining for vimentin and negative staining for cytokeratin AE1/AE3 was found in both specimens which supports the diagnosis of sarcoma." (PMID 26252375, 2015).
bladder cancer (104 papers, 2011 to 2026). "Our findings underscore that TWIST1/Vimentin promoter hypermethylation is significantly associated with the risk of bladder cancer, corroborating several prior studies." (PMID 38575639, 2024). "Vimentin (VIM), a key marker of mesenchymal cells, has been found to be associated with tumor growth, invasion, and unfavourable prognosis in bladder cancer." (PMID 37915048, 2023). "PTEN deficiency in T24 and HT-1376 bladder cancer cells noticeably attenuated the sh-Jumonji AT-rich interactive domain 2-mediated increase of E-cadherin and decrease of vimentin and N-cadherin expression." (PMID 33423167, 2021). "For example, associations of VIM with genes, gene products, miRNAs, copy number alterations, methylation and protein levels within bladder cancer were explored." (PMID 33299129, 2021). "Sorted samples were evaluated with EMT and bladder cancer associated markers, namely CK, VIM, and survivin." (PMID 31480265, 2019). "A recent study showed that expression of HMGA2, loss of E-cadherin, and expression of vimentin are significantly correlated with bladder cancer grade and stage." (PMID 26640315, 2015). "In this study, we utilize a Methylation Assay Kit designed explicitly for the Twist1/Vimentin gene (produced by Jiangsu MicroDiag Biomedicine Co., Ltd., China), intending to assess its diagnostic precision and clinical applicability in patients with bladder cancer." (PMID 38575639, 2024). "The effects of FAM171B on modulating tumor-associated macrophages (TAMs) and vimentin-mediated tumor progression, as well as the underlying mechanisms, were clarified by phalloidin staining, immunofluorescence staining, ELISA, RNA immunoprecipitation, flow cytometry and a bladder cancer graft model." (PMID 37915048, 2023). "The epigenetic dysregulation of VIM would promote epithelial‐mesenchymal transition, leading to invasion and metastasis of bladder cancer." (PMID 41505248, 2026). "Hypermethylation of individual biomarkers TWIST1, hTERT, NID2, and VIM was detected with a sensitivity of 92%, 97%, 84%, and 83%, respectively, and a specificity of 100% for each using urine sediment samples in Moroccan bladder cancer patients." (PMID 40141826, 2025). "We revealed that SBSPON regulates the expression of EMT-related markers, such as E-cadherin, N-cadherin, Vimentin and Snail, leading to reduced migration and invasion of bladder cancer cells." (PMID 40765821, 2025). "Future research focusing on this pathway’s effects on key EMT transcription factors and biomarkers (such as E-cadherin, N-cadherin, and vimentin) will be crucial for comprehensively elucidating its role in bladder cancer dissemination." (PMID 41357604, 2025). "SFN down-regulated adhesion and migration in chemo-sensitive and chemo-resistant bladder cancer cells by acting on integrin β1 and β4 expression and inducing the mesenchymal–epithelial translocation of cadherins and vimentin." (PMID 38474751, 2024). "The results showed that circLRIG1 overexpression increased the protein level of E-cadherin while reducing the protein level of N-cadherin and Vimentin in bladder carcinoma cells." (PMID 38454507, 2024). "Activation of the RAS/ERK pathway can induce the occurrence of EMT in bladder cancer through various mechanisms, affecting the expression and function of N-cadherin, vimentin, and E-cadherin." (PMID 39769029, 2024). "This contrasts with reports indicating a correlation between vimentin expression and acquiring an invasive and metastatic bladder cancer phenotype." (PMID 38474751, 2024). "We identified vimentin as an important interacting protein of FAM171B in the cytoplasm of bladder cancer cells." (PMID 37915048, 2023). "In summary, these results confirm that FAM171B contributes to bladder cancer progression by stabilizing vimentin both in vivo and in vitro." (PMID 37915048, 2023).
bladder cancer (continued). "The upregulation of vimentin during EMT in bladder cancer cells implies that targeting vimentin has potential as a therapeutic strategy to impede the progression of metastatic disease." (PMID 37915048, 2023). "In this study, we revealed that FAM171B promotes bladder cancer progression through its interaction with vimentin, highlighting FAM171B as a critical regulator of cancer metastasis." (PMID 37915048, 2023). "Vimentin, an intermediate filament protein associated with EMT, has been reported to be linked with increased tumor growth, invasion, and poor prognosis in bladder cancer." (PMID 37915048, 2023). "In concordance with observations in human UC, we observed abundant and specific staining of vimentin in the vasculature of canine bladder cancer tissues, underscoring the relevance of our approach of targeting vimentin with a vaccine." (PMID 37568772, 2023). "Knockdown of LINC02470 also reduced the levels of two typical mesenchymal markers, vimentin and N-cadherin, in both bladder cancer cell lines." (PMID 35205713, 2022). "Preclinical studies in rodents, as well as the efficacy study in client-owned dogs with spontaneous bladder cancer, show that vaccination against extracellular vimentin is safe, emphasizing the specificity of extracellular vimentin for tumor angiogenesis." (PMID 35606362, 2022). "In a study focusing on E-cadherin, vimentin, and Twist expression in bladder cancer, only vimentin seemed to be an independent predictor of cancer progression and reduced survival." (PMID 36669020, 2022). "Apart from being highly expressed in cisplatin-sensitive bladder cancer cell lines compared to its resistant counterpart, knockdown of FDFT1 in bladder cancer cells has resulted in acquisition of mesenchymal morphology and increased vimentin expression." (PMID 35093030, 2022). "Curcumin inhibited smoke-induced EMT as shown by an increase in the epithelial marker E-cadherin and zona occludens-1 (ZO-1) and a decrease in mesenchymal markers vimentin and N-cadherin in bladder cancer." (PMID 33572742, 2021). "Studies have also shown that increased PLEC and vimentin expression, through PLEC complex regulation of vimentin assembly, correlate with invasive phenotypes in bladder cancer and invasion and metastasis in androgen-independent prostate cancer." (PMID 34001250, 2021). "The expression levels of E-cadherin and vimentin in bladder cancer cells were detected by Western blot." (PMID 33898446, 2021). "It turned out that knockdown of lncRNA SNHG3 inhibited GINS2, N‐cadherin and vimentin expression, and up‐regulated E‐cadherin expression of bladder cancer in vivo." (PMID 32596993, 2020). "Our results showed that low-grade bladder cancer cells (TSGH-8301) treated with high-grade bladder cancer cell-derived exosomes (T24-Exos or J82-Exos) had an increase in mesenchymal proteins (N-cadherin and vimentin) and a decrease in E-cadherin." (PMID 32517366, 2020). "Herein, HMGN5 or Hsp27 overexpression significantly promoted EMT by increasing E-cadherin and decreasing Vimentin, and promoted the invasion of bladder cancer cells." (PMID 32315283, 2020). "The key regulators of the EMT process are E-cadherin, N-cadherin, vimentin, Snail, Slug, Twist, and Zeb-2, and most of these have been correlated with bladder cancer progression via either genetic or epigenetic regulation." (PMID 32517366, 2020). "In contrast to HMGN5 or Hsp27 overexpression, HMGN5 or Hsp27 silencing significantly inhibited bladder cancer cell invasion and increased the E-cadherin expression and decreased Vimentin expression." (PMID 32315283, 2020). "We found that iCAFs promotes the upregulation of mesenchymal markers, such as N-cadherin and vimentin, while repressing epithelial markers E-cadherin and p-ß-catenin expression in bladder cancer cells." (PMID 30744595, 2019).
bladder cancer (continued). "In order to explore the molecular mechanism of ZFAS1 in bladder cancer, we detected the effect of ZFAS1 on the expression of KLF2, NKD2, and EMT-associated genes (ZEB1, E-Cadherin, and Vimentin) by Western blot." (PMID 29678899, 2018). "Knockdown of DANCR increased E-cadherin expression and decreased N-cadherin and vimentin expression in bladder cancer cells." (PMID 30419948, 2018). "Positive staining of vimentin was observed in the cytoplasm, and vimentin expression in bladder cancer tissue samples (71.6%, 73/102) was significantly higher than that in adjacent (21.6%, 22/102) and normal bladder tissue samples (11.3%, 12/106) (P < 0.05)." (PMID 29349903, 2018). "In this study, the results showed that knocking down Kindlin-2 in CAFs led to increased E-cadherin expression, and decreased N-cadherin and vimentin expression in co-cultured bladder cancer cells." (PMID 28881595, 2017). "In contrast, downregulation of HES1 in bladder cancer enhanced vimentin and reduced E-cadherin levels, which triggers an EMT phenotype and malignant progression." (PMID 28122586, 2017). "They concluded that Vimentin is potential independent indicators in predicting bladder cancer progression and survival." (PMID 28166762, 2017). "The changes we found in vimentin were comparable to changes in cell morphology and vimentin expression reported by others in bladder carcinoma cells." (PMID 27049728, 2016). "Consistently, the potential bladder cancer marker - Vimentin was downregulated in cytoplasmic region of all BCa cells treated with simvastatin." (PMID 27779188, 2016). "The prognostic significance of E-cadherin, twist, and vimentin was assayed in 121 patients with bladder cancer and, in this study, only vimentin appears as an independent predictor for cancer progression and survival." (PMID 26425122, 2015). "Loss of expression of miRNA-141 and miRNA-200b was associated with increased invasion and migration ability, upregulated MMP-2, MMP-9, vimentin and N-cadherin expression, and downregulated E-cadherin expression in bladder cancer cell lines." (PMID 25884322, 2015). "Here, we determined the expression of epithelial marker, E-cadherin, and mesenchymal marker, vimentin and N-cadherin in bladder cancer cells with altering expression of miR-186 and NSBP1." (PMID 26290438, 2015). "Some human bladder cancer cells and stromal cells in the clinical cancer specimens, as well as cancer cells in PDXs, were stained positive for human vimentin." (PMID 26270481, 2015). "A study finding showed that 30 (24.8%) were positive for vimentin in bladder cancer patients and other important investigations showed that 43.00% bladder cancer expressed vimentin." (PMID 26640315, 2015). "In this vista, our study tried to find some more information of CK and vimentin role in the diagnosis of bladder carcinoma/Transitional Cell Carcinoma." (PMID 26640315, 2015). "Here, we characterized ten human bladder cancer cell lines with respect to expression of E-cadherin, N-cadherin and vimentin." (PMID 24325461, 2013). "Our study also represents the first report demonstrating the IL6-regulated expression of the E-cadherin, N-cadherin, and vimentin protein in bladder carcinoma cells." (PMID 23762858, 2013). "Our data confirm that mesenchymal markers (Zeb-1, Zeb-2, MMPs, and vimentin) are expressed almost exclusively by muscle-invasive tumors, the subset of bladder cancer with worse outcome." (PMID 22253920, 2012). "Methylation levels of EOMES, HOXA9, POU4F2, TWIST1, VIM, and ZNF154 in urine specimens are promising diagnostic biomarkers for bladder cancer recurrence surveillance." (PMID 23056278, 2012). "We also examined the cell surface expression of E-cadherin, as an epithelial marker, and vimentin, as a mesenchymal marker, in the three bladder cancer cell lines treated with the three Cox-2 inhibitors using the FCM." (PMID 21750550, 2011).